IL6 (interleukin 6)
Diseases named in the same sentence as IL6 in open-access papers (continued):
Sharing a sentence is not in itself a finding about the gene and the disease.
Obesity (continued). "These molecules are associated with pro-inflammatory activity and are involved in the development of IR, with elevated circulating levels of TNF-α and IL-6 found in subjects with obesity and IR." (PMID 39310407, 2024). "The hyperplasia andhypertrophy of adipose tissues caused by obesity are often driven by theexcessive release of pro-inflammatory cytokines from these tissues, known asadipokines, including TNF-α, IL-6, and interleukin-3 (IL-3)." (PMID 39742220, 2024). "VAT metaflammation in obesity, as measured by mRNA levels of TNF-α, IL6, and MCP-1/CCL2, is associated with insulin resistance and cellular senescence." (PMID 39063184, 2024). "In another Spanish study in children with obesity and insufficient vitamin D status, elevated IL-6 concentrations were observed." (PMID 39231874, 2024). "At baseline, obesity and steatosis were associated with increased serum concentrations of CRP, IL-6 and TNFα." (PMID 39200991, 2024). "The results indicated the presence of inflammation in males from obesity induction groups 1 and 2, characterized by higher relative expression of il-1-β, il-6, and tnf-α." (PMID 39408365, 2024). "Mature-onset obesity has been reported for various murine knockout models, e.g. for IL-1R, IL-6, p62, TLR2 and OTR, and is now also linked with HDAC5 deficiency." (PMID 39304061, 2024). "Single logistic regression showed that logTSH, low ferritin status, high CRP, high IL-6, obesity as well as low hCG concentrations and increasing age were all significantly associated with IH." (PMID 38330593, 2024). "Some of them (like IL-6) have anti-inflammatory activity in the physiological state, while they gain pro-inflammatory properties in the obesity state." (PMID 38397196, 2024). "In the spleen, the major lymphoid organ responsible for systemic immune response, TNF-α and IL-6 expression in this organ decreased significantly with obesity." (PMID 39274918, 2024). "Regarding metabolic disturbances, it was observed that miR-146a is downregulated in obesity and correlates negatively with IL-6, TNF-α, and CD36." (PMID 38610754, 2024). "The results indicate that the obesity induction diets tested generated inflammation in zebrafish and, in this study, for IL-6, sex influenced the outcome." (PMID 39408365, 2024). "Immunosuppression and disproportionate cytokine activation are exacerbated by the chronic low-grade inflammatory characteristic of obesity, which is characterized by increased activation of circulating cytokines, particularly Interlukin-6 (IL-6)." (PMID 39188722, 2024). "Obesity-related inflammation is linked to pro-inflammatory cytokines such as TNF-α, IL-6, uric acid, and CRP, which interfere with normal GnRH secretion from the hypothalamus and reduce testosterone production." (PMID 39473678, 2024). "The accumulation of visceral adipose tissue macrophages is also a hallmark of obesity, and these cells secrete pro-inflammatory cytokines like TNF, IL-6, and IL-1ß, driving systemic, chronic, low-grade inflammation." (PMID 39050851, 2024). "People with obesity experience chronic inflammation due to the endocrine function of adipocytes, which leads to a release of such pro-inflammatory cytokines as IL-6, IL-1β, and TNF-α." (PMID 39456224, 2024). "In high-fat diet-induced obesity, hepatic inflammation resulting from sustained IL-6 or IL-11 activation leads to steatohepatitis and hepatitis." (PMID 38999780, 2024). "IL-18 has increased expression in obesity and can induce the production of copious amounts of IL-6, serving as an amplifier of IL-6 effects." (PMID 39063055, 2024). "Primarily produced by the liver, CRP is also synthesized in patients with obesity in response to inflammatory mediators, mainly interleukin-6 (IL-6)." (PMID 39141186, 2024). "Obesity and overweightness are well-known proinflammatory metabolic disorders relating to high levels of inflammatory markers including interleukin (IL-)1β, IL-6, C-reactive protein, and tumor necrosis factor (TNF)α." (PMID 39337202, 2024).
Obesity (continued). "To verify the effect of IL-6 signaling on obesity-driven ATM proliferation in vivo, we used a myeloid-specific knockout of the IL-6Rα (Il6raΔmyel)." (PMID 38482013, 2024). "During the progression of obesity, adipocytes play a role in promoting inflammation by releasing typical proinflammatory cytokines, including IL-1, IL-6, COX-2, and TNF-α." (PMID 39281480, 2024). "Extensive evidence supports the connection between obesity-induced inflammation and the heightened expression of IL-6 adipose tissues." (PMID 38928498, 2024). "To assess the association between chronic low-grade inflammation and obesity, we measured the levels of hs-CRP, IL-6, and TNF-alpha." (PMID 39200519, 2024). "Adipocytes and macrophages within adipose tissue secrete TNF-α and IL-6, which influence the relationship between obesity and periodontitis." (PMID 39310407, 2024). "Increased levels of TNFα and IL-6, commonly encountered in obesity, augment superoxide anion production and nicotinamide adenine dinucleotide phosphate (NADPH) oxidase (NOX) activity." (PMID 38247541, 2024). "IL-6 was identified as a lipolytic factor, as the IL-6 knockout mice developed mature obesity, which was partially reversed after repeated administration of IL-6." (PMID 38799170, 2024). "Thus, individuals with this particular IL-6 variant may have a slightly higher likelihood of being overweight or obese compared to those without it, but this is just one of many factors influencing obesity risk." (PMID 39769263, 2024). "Interleukin-6 (IL6), a proinflammatory cytokine, is shown to have strong associations with obesity, insulin resistance, type 2 diabetes and liver disease." (PMID 38614964, 2024). "Between IL-6 and Leptin concentrations, a positive average correlation is observed for patients with normal body mass, overweight, and obesity (Pearson: 0.51, p = 0.006)." (PMID 38786737, 2024). "Individuals with obesity display elevated levels of pro-inflammatory cytokines such as interleukin-6 (IL-6) and TNF-α." (PMID 39121085, 2024). "In the ANS/inflammation-induced obesity network, the fibrilin 1 (FBN1) gene, encoding the asprosin hormone, interacts only with IL6, which, in turn, interacts with interferon gamma (IFNG)." (PMID 39062927, 2024). "CRP, an acute-phase protein, is released in response to inflammation triggered by IL-6 secretion and is considered an additional marker of metabolic syndrome, with elevated levels often seen in obesity and insulin resistance." (PMID 39468643, 2024). "Interleukin 6 (IL-6) levels increase in individuals with obesity as there is greater expression in increased visceral fat tissue." (PMID 39771030, 2024). "Obesity is an inflammatory condition, characterised by higher levels of inflammatory markers including Interleukin-6." (PMID 39770979, 2024). "Increased inflammatory cytokines such as interleukin 6 and tumor necrosis factor alpha (TNFα) are hallmarks of obesity, and promote the secretion of hepatic C-reactive protein (CRP) which further induces systematic inflammation." (PMID 38742193, 2024). "In obesity-associated CRC, NFκB is a critical regulator of inflammation through IL-6 production and TNFα activation." (PMID 39201522, 2024). "While obesity was associated with upregulation of many effector molecules, TNF-α, COX-2 and IL-6 expression showed the strongest responses." (PMID 38672413, 2024). "Mate treatment reduced Il6 expression in WAT during the development of obesity and insulin resistance." (PMID 38327997, 2024). "Inflammatory processes associated with obesity and metabolic syndrome, including the release of pro-inflammatory cytokines like TNF-α and IL-6, create a tumor-promoting environment that enhances cancer cell proliferation, invasion, and resistance to apoptosis." (PMID 39518104, 2024).
Obesity (continued). "Intriguingly, in obese mice fed a HFD and animal models of obesity induced by monosodium glutamate, a downward trend in IL-6 expression has been observed in conjunction with the occurrence of skeletal muscle dysfunction." (PMID 39858415, 2024). "Our study found significantly higher levels of IL-6 in the obesity group compared to the control group (normal body weight) in both women and men." (PMID 39769504, 2024). "Obesity was also associated with higher levels of inflammatory markers, such as CRP and interleukin-6 (IL-6), indicating an increased inflammatory state." (PMID 39518325, 2024). "Another study reported that placentas from women with obesity develop exaggerated inflammatory responses with increased macrophages infiltration and pro-inflammatory cytokines (TNFa and IL-6)." (PMID 38145995, 2024). "Obesity is known to activate inflammatory responses with increased production in pro-inflammatory IL-6 in the periodontium, triggering periodontal inflammation." (PMID 39851590, 2024). "Compared with the high-calorie diet groups, phentermine groups, and orlistat groups, Qu can significantly inhibit the expression of pro-inflammatory genes such as IL-6, IL-1β, IL-18, and TNF-α, thereby alleviating the inflammatory state caused by obesity." (PMID 39712006, 2024). "Risk factors for GD, such as obesity, are associated with increased numbers of resident adipose tissue macrophages that secrete pro-inflammatory cytokines, including TNF-α, IL-6, and IL-1β." (PMID 39456486, 2024). "Similar to irisin, IL-6 produced by skeletal muscle is involved in the modulation of chronic diseases such as obesity." (PMID 39456138, 2024). "A weak positive correlation is observed between the concentrations of IL-6 and hsCRP for patients with normal body mass, overweight, and obesity (Pearson: 0.6, p = 0.0009)." (PMID 38786737, 2024). "Individuals with obesity exhibit markedly reduced immunological tolerance, leading to excessive production of inflammatory mediators such as IL-6, TNF-α, IL-1β, and IFN-γ, alongside a significant decrease in anti-inflammatory cytokines like IL-4 and IL-10." (PMID 38840158, 2024). "IL-6 plays an important role in regulating body fat, as it is released from adipocytes and its levels are elevated in obesity, indicating the presence of an inflammatory state." (PMID 38958868, 2024). "M1-macrophages release high levels of TNF-α in obesity which, in turn, provide an inflammatory stimulus that increases the production of IL-6, leptin and plasminogen activator inhibitor-1 (PAI-1)." (PMID 38133765, 2024). "Obesity is associated with inflammation and elevated cytokines such as TNF-α and IL-6, which can lead to tissue damage and contribute to conditions like NAFLD." (PMID 39202687, 2024). "On the other hand, IL-6 is elevated in obesity and with exercise, and thus, its effects on insulin signaling are controversial." (PMID 38999834, 2024). "More interestingly, FBN1 interacts directly with IFNG in stress-induced obesity but with IL6 in ANS/inflammation-induced obesity." (PMID 39062927, 2024). "As the concentration of IL-6 rises, there is a corresponding increase in the concentration of Leptin for patients with normal body mass, overweight, and obesity." (PMID 38786737, 2024). "On the contrary, GRN can exhibit a pro-inflammatory effect by promoting the expression of proinflammatory cytokines such as IL-6 and IL-8 in different diseases such as psoriasis, obesity, and systemic lupus erythematosus." (PMID 38854033, 2024). "In obesity, there is an increased expression of proinflammatory cytokines and hormones that are produced within adipose tissue, such as interleukin-6 (IL-6), tumor necrosis factor-alpha (TNFa), leptin, angiotensinogen, resistin, and C-reactive protein." (PMID 38672532, 2024).
Obesity (continued). "Obesity is a low-grade inflammation characterized by increased production and secretion of inflammatory cytokines, such as interleukin-6 and tumor necrosis factor-α, which stimulate the liver to synthesize and release CRP into circulation." (PMID 39765954, 2024). "Diabetes and obesity compose an inflammatory state leading to heightened secretion of cytokines such as IL-6 and, eventually, the formation of HFpEF." (PMID 39769189, 2024). "Individuals with obesity showed higher plasma levels of IL-6 (median 1.79 vs. 0.50 pg/mL in controls) and hsCRP (median 2.10 vs. 0.24 mg/dL in controls)." (PMID 38741712, 2024). "The results also showed significantly higher IL-6 levels in the obesity group compared to the control group in both women and men." (PMID 39769504, 2024). "Contributing to immunosuppressive macrophage polarization and immunosuppression in general, are myeloid derived suppressor cells (MDSCs), which have been observed to be elevated in obesity in part due to increased IL-6 and other pro-inflammatory cytokines." (PMID 38800540, 2024). "For example, Il6−/− mice developed mature-onset obesity and decreased glucose tolerance, which was partly reversed by IL-6 replacement at low doses." (PMID 38890694, 2024). "Due to the large number of possible disorders, it is important to control markers of inflammation in obesity, including the tested IL-6 to react as quickly as possible." (PMID 38786737, 2024). "There were no clear sex differences in cytokine production capacity, although some cytokines were higher in females with obesity compared to males (for IL-1β, IL-6, TNF), in line with findings on activation markers by flow cytometry." (PMID 38741712, 2024). "There is a widespread upregulation of pro-inflammatory signaling cascades in obesity including mediators like IL-6 and TNFα." (PMID 38512816, 2024). "Higher concentrations of interleukin (IL)-6, commonly found in patients with obesity and/or T2D trigger the expression of liver hepcidin via the JAK-STAT3 pathway." (PMID 40895225, 2024). "We identified four factors, FEV1, FVC, CRP, and IL-6, that mediated the effects of obesity on LRTIs." (PMID 39337223, 2024). "In chronic renal failure related to obesity, TNF-α, IL-1β, and IL-6 genetic overexpression was associated with chronic inflammation in adipose tissue." (PMID 39274918, 2024). "Cytokines that are classically upregulated in obesity, such as TNFα, IL-6, and TGFβ, promote tumour cell proliferation and invasion, and possible tumour formation." (PMID 38248845, 2024). "Obesity is characterized by excessive adiposity and elevated levels of pro-inflammatory adipokines, such as tumor necrosis factor alpha and interleukin-6, resulting in a chronic low-grade inflammatory state." (PMID 39458427, 2024). "CRP, IL-6, and FEV1 play crucial intermediary roles in the association of obesity with pneumonia, and CRP, FVC, and FEV1 mediate the effect of obesity on acute bronchitis." (PMID 39337223, 2024). "It is expected that targeting the disruption of pathways mediated by FVC, FEV1, CRP, and IL-6 can reduce the adverse impact of obesity on acute bronchitis and pneumonia, thereby alleviating the burden of LRTIs." (PMID 39337223, 2024). "In mouse adipose tissue, nesfatin-1 expression and secretion increase with diet-induced obesity and are influenced by pro-inflammatory cytokines (IL-6, TNF-α) and insulin." (PMID 39455994, 2024). "Because IL-6, COX2/PGE2, and M2a macrophage activation have been proven to protect against obesity, our results indicate that the Klf9 transgene in macrophages promotes obesity by inhibiting M2a macrophage polarization and IL-6 and PGE2 secretion." (PMID 38331933, 2024). "Cytokines such as IL-6 stimulate the HPA axis to promote obesity or insulin resistance through a network of mechanisms involving the resistance of glucocorticoid receptors to cortisol." (PMID 38892598, 2024).
Obesity (continued). "Adipose tissue releases adipocytokines, including TNF-α, IL-6, leptin, and adiponectin, and elevated serum leptin and reduced serum adiponectin levels are characteristic features of obesity." (PMID 38542720, 2024). "Another mechanism underlying low iron levels in obesity is chronic inflammation; adipose tissue secretes multiple pro-inflammatory cytokines including tumor necrosis factor (TNF)-α and interleukin-6 (IL-6)." (PMID 38672754, 2024). "The volcano plot also confirmed significant downregulation of various genes in inflammation and obesity including IL-6, IL-1B, CCL2, PPARg, and Fabp4." (PMID 38512816, 2024). "In the context of obesity, there is an upregulation of IL-6 expression in adipose tissue, which exacerbates metabolic inflammation." (PMID 39201638, 2024). "Some studies also found that elevated levels of pro-inflammatory cytokines, such as IL-1β, IL-6, and TNF-α, associated with obesity can impair sleep architecture and promote sleep disturbances." (PMID 39267856, 2024). "Obesity particularly increases the pro-inflammatory factors interleukin-1 (IL-1), IL-6, and tumor necrosis factor-alpha (TNFα), which in turn stimulate the liver to produce other cytokines." (PMID 38915014, 2024). "Central activation of the IL-6 trans-signaling has been reported to improve glucose metabolism in mouse models of obesity." (PMID 39723211, 2024). "For example, circulating adipose-derived cytokines, such as tumour necrosis factor-α (TNF-α) or interleukin-6 (IL-6) are elevated in obesity." (PMID 39339770, 2024). "Our main objective was to evaluate the levels of adiponectin, leptin, TNFα, IL6, IGFs 1 and 2 in endometrial cancer patients compared to control patients and to examine their relationship with obesity." (PMID 38339282, 2024). "It is known that obesity and insulin resistance are conditions where low-grade inflammation prevails, characterized by the secretion of pro-inflammatory cytokines (IL-1, IL-6, TNF-α)." (PMID 38474087, 2024). "As already mentioned, an important role is thought to be played by increased systemic levels of inflammatory mediators, such as IL-6, which is frequently observed in obesity and MASLD." (PMID 39456575, 2024). "Nevertheless, administration with FLT, FBT, or orlistat for eight weeks significantly suppressed the liver’s TNF-α, IL-1β, and IL-6 expression levels (p < 0.05), thus alleviating the inflammation induced by obesity." (PMID 38254507, 2024). "Leptin resistance and inflammation demonstrated by higher plasma and central nervous system levels of interleukin-6 (IL-6), IL-1β and tumour necrosis factor-α, are mechanisms connecting obesity and diabetes with AD." (PMID 38290839, 2024). "An animal study showed that obesity caused deficiency of PGC-1α in the pancreas, which significantly enhanced NF-kB-mediated up-regulation of IL-6 in pancreas, resulting in serious inflammatory responses." (PMID 37526777, 2023). "Obesity is considered a low-grade chronically inflamed state that presents higher levels of IL-6 and CRP in the body." (PMID 37566728, 2023). "The results of a meta-analysis suggest that individuals with periodontitis and obesity have higher baseline serum levels of IL-6." (PMID 37798684, 2023). "Inflammatory pathways, including NF-κB signaling, are aggravated in adipose tissues affected by obesity, resulting in the elevated expression of subsequent cytokines such as TNFα, IL6, IL1β, and others." (PMID 37764703, 2023). "During the last decade, several studies have suggested that obesity is associated with an inflammatory process characterized by increased plasma levels of proinflammatory cytokines such as TNF-α, IL-6, and C-reactive protein." (PMID 36902133, 2023). "Adiponectin, leptin, IL-6, TNF-α and MCP-1 plasma levels were measured by enzyme-linked immuno assays for 60 subjects with FPLD2 and for 60 subjects with obesity." (PMID 37081489, 2023).